RNU11 (RNA, U11 small nuclear)
Synonyms: U11; RNU11-1
Gene: Small nuclear RNA gene on chromosome 1 (28,648,600 to 28,648,734, forward strand). Ensembl gene ENSG00000274978.
Pathways (Reactome):
Gene expression (Transcription): RNA polymerase II transcribes snRNA genes
Gene Ontology:
Molecular function: pre-mRNA 5'-splice site binding
Biological process: mRNA 5'-splice site recognition
Cellular component: U11 snRNP
Diseases named in the same sentence as RNU11 in open-access papers:
RNU11 is named in the same sentence as 8 diseases in open-access papers, as found by Europe PMC text mining. Sharing a sentence is not in itself a finding about the gene and the disease. The quoted sentences say what the papers report.
microcephaly (2 papers, 2022 to 2023). A congenital or acquired developmental disorder in which the circumference of the head is smaller than normal for the person's age and sex.
microcephalic osteodysplastic primordial dwarfism (1 paper, 2022). "RNU11 gene belongs to the snRNA class, and the mutation in this gene is associated with Microcephalic Osteodysplastic Primordial Dwarfism, Type I." (PMID 35436926, 2022).
PRLomas (1 paper, 2019). "However, PLS-DA analysis neatly revealed a different expression pattern between PRLomas and NPs, and VIP score analysis identified three components with high capacity to discriminate between both populations (RAVER1, MAGOH, and RNU11)." (PMID 31561558, 2019).
tumor (3 papers, 2013 to 2021). "U11 (RNU11) is probably the most significant small nuclear RNA because its expression is extremely high expressed in rapidly growing tumor cells and very low expressed in slow-growing primary cells." (PMID 34276798, 2021).
RNU11 also shares sentences with these, for which no sentence is quoted: amyotrophic lateral sclerosis (1 paper); asthma (1); cancer (1); myeloma (1).